RNU7-187P (RNA, U7 small nuclear 187 pseudogene)
Gene: Small nuclear RNA gene on chromosome 11 (112,977,353 to 112,977,420, forward strand). Ensembl gene ENSG00000238998.
Homologues: Orthologues: chimpanzee U7 (99% identical), macaque U7 (79% identical). Paralogues in human: RNU7-152P (76% identical), RNU7-34P (76% identical), RNU7-35P (76% identical), RNU7-73P (76% identical), RNU7-148P (75% identical), RNU7-51P (75% identical), RNU7-62P (75% identical), RNU7-70P (75% identical), RNU7-82P (75% identical), RNU7-88P (75% identical), RNU7-127P (74% identical), RNU7-128P (74% identical), and 142 more.